DDR2 (discoidin domain receptor tyrosine kinase 2)
Diseases named in the same sentence as DDR2 in open-access papers (continued):
Sharing a sentence is not in itself a finding about the gene and the disease.
ovarian carcinoma (20 papers, 2014 to 2025). A malignant neoplasm originating from the surface ovarian epithelium. "Immunohistochemical evaluation of advanced stage, human ovarian cancer specimens demonstrate that high expression of DDR2 in tumors is associated with poor survival." (PMID 37996700, 2024). "Discoidin domain receptor 2 (DDR2) expression is upregulated in ovarian cancer tissues, and is closely associated with poor clinical outcomes in ovarian cancer patients." (PMID 34065317, 2021). "In the present study, we identify the underlying mechanism by which LPA induces the expression of another receptor tyrosine kinase, DDR2, which is closely associated with ovarian cancer progression." (PMID 34065317, 2021). "Since DDR2 is predominantly expressed by mesenchymal cells, we asked whether presence of DDR2 in ovarian cancer-associated stromal cells impacted ovarian tumor burden in mouse models." (PMID 37996700, 2024). "We confirmed that DDR2 regulates POSTN expression in ovarian cancer-associated fibroblasts (CAFs)." (PMID 35884543, 2022). "Curiously, in our studies, single knockdown of a either integrin α1β1 or DDR2 has been sufficient to attenuate most COL11A1 downstream signaling in ES2 ovarian cancer cells, although DDR2 knockdown caused more inhibition of COL11A1 downstream signaling than ITGα1 knockdown." (PMID 33668097, 2021). "In addition, this collagen receptor DDR2 expression is upregulated in ovarian cancer tissues, and is associated with poor clinical outcomes in ovarian cancer patients." (PMID 34065317, 2021). "Moreover, we observed that HIF-1α, located downstream of the mTOR, is implicated in LPA-induced DDR2 expression and ovarian cancer cell invasion." (PMID 34065317, 2021). "This axis engages in a functional interaction with discoidin domain receptor 2 (DDR2) mRNA, enhancing the expression of the pro-tumorigenic protein DDR2 and thereby fueling ovarian cancer malignancy." (PMID 40986143, 2025). "In ovarian cancer, DDR2 stabilizes EMT transcription factors, such as Snail1, thus maintaining mesenchymal characteristics and promoting tumor invasion and metastasis." (PMID 40563472, 2025). "CAFs enhance ovarian cancer invasion and metastasis through DDR2-regulated periostin 27 and promote colorectal cancer metastasis through IL-6-mediated LRG1 upregulation." (PMID 37056933, 2023). "Stromal DDR2 protein expression was highly correlated with stromal POSTN protein expression in ovarian cancer patients (Spearman rho = 0.77, p < 0.0001)." (PMID 35884543, 2022). "To determine if DDR2 protein expression was correlated with POSTN protein expression in ovarian cancer patients, we performed immunohistochemistry on a tumor microarray with specimens from 180 patients with primary and metastatic tumor sites." (PMID 35884543, 2022). "In conclusion, we have identified that DDR2-expressing CAFs regulate POSTN through ITGB1 to promote tumor metastasis in ovarian cancer." (PMID 35884543, 2022). "In ovarian cancer, activation of DDR2 seems to enhance ovarian cancer cell survival by activating the Src-AKT pathway." (PMID 36249782, 2022). "Lastly, LPA produced MT1-MMP, which has been shown to be a downstream proteolytic factor of DDR2 for ovarian cancer cell invasion." (PMID 34065317, 2021). "We have previously reported that COL11A1 activates Src-Akt signaling through the collagen receptors discoidin domain receptor 2 (DDR2) and integrin α1β1 to confer cisplatin resistance to ovarian cancer cells." (PMID 34638339, 2021). "Together, these data indicate that DDR2 expression is important in LPA-induced ovarian cancer cell invasion." (PMID 34065317, 2021). "We also found ectopic expression of ATX or stimulation of ovarian cancer cells with LPA-induced DDR2 expression." (PMID 34065317, 2021). "Collagen XIα1 binding to both integrin α1β1 and DDR2 mediates chemoresistance by activating signaling that inhibits cisplatin-induced apoptosis in ovarian cancer cells." (PMID 34805157, 2021).
ovarian carcinoma (continued). "In the present study, we determined a critical role and signaling cascade for the expression of DDR2 in LPA-induced ovarian cancer cell invasion." (PMID 34065317, 2021). "While we have focused here on DDR1 and DDR2 in breast and ovarian cancer, they are increasingly important and relevant anti-cancer targets for multiple tumor types." (PMID 34805157, 2021). "Discoidin domain receptor Tyrosine Kinase 2 is highly expressed in ovarian cancer tissues and has been shown to enhance the invasive ability of tumor cells." (PMID 34805157, 2021). "Through receptor knockdown and inhibitor experiments, we demonstrated that COL11A1 significantly upregulates HSP27 phosphorylation and expression via DDR2/integrin α1β1 and Src/Akt signaling in ovarian cancer cells." (PMID 34638339, 2021). "Since ovarian cancer 2780 and ES2 cells express the DDR2 protein associated with ovarian cancer metastasis, we first stimulated these cells with LPA and observed markedly upregulated DDR2 expression in a dose-dependent manner." (PMID 34065317, 2021). "Like DDR1, DDR2 is involved in the modulation of MMP expression in ovarian cancer where it regulates the expression of MMP1–3, 7, and 13 mRNAs and the activity of MMP2 and MT1-MMP." (PMID 33917302, 2021). "We in the present study provide evidence that ATX, and thereby LPA, aggravates ovarian cancer cell invasion through DDR2 expression." (PMID 34065317, 2021). "In this study, we report that COL11A1 upregulates HSP27 expression and activity through DDR2/integrin α1β1-Src-Akt signaling to induce cisplatin resistance in ovarian cancer cells." (PMID 34638339, 2021). "DDR2 upregulation was detected in 103 ovarian cancer tissues, correlates with tumor stage and peritoneal metastasis, and is an independent prognostic factor." (PMID 34805157, 2021). "This notion of switching between DDR1 and DDR2 has been recently suggested in ovarian cancer, where DDR2 mRNA expression is low in epithelial-like cells and increases in mesenchymal-like cells." (PMID 33917302, 2021). "Previously, DDR2 was reported to induce ovarian cancer cell invasion through the expression of various proteolytic enzymes." (PMID 34065317, 2021). "We show that COL11A1 upregulates both fatty acid synthesis and oxidation predominantly through DDR2-Src-Akt-AMPK dependent signaling to inhibit cisplatin-induced apoptosis in ovarian cancer cells." (PMID 32312965, 2020). "Collectively, our results demonstrate that COL11A1 increases de novo fatty acid synthesis through DDR2-Src-Akt-AMPK signaling to upregulate FAO in ovarian cancer cells." (PMID 32312965, 2020). "Taken together, our results suggest that COL11A1 upregulates fatty acid metabolism in ovarian cancer cells in a DDR2-Src-Akt-AMPK dependent manner." (PMID 32312965, 2020). "Twist1 promotes ovarian cancer metastasis by upregulating discoidin domain receptor 2 (DDR2), a receptor tyrosine kinase (RTK) that recognizes fibrillar collagen as a ligand and enhances mesothelial clearance, invasion, and migration through matrix remodeling and Snail1 stabilization." (PMID 39796130, 2024). "Our findings reveal how CAFs are a major source of arginase activity and L-arginine metabolites in ovarian tumors and that DDR2 and arginase in CAFs may be a target in ovarian cancer." (PMID 37996700, 2024). "Identifying downstream targets of DDR2 may allow specific modulation of ovarian cancer metastatic pathways." (PMID 35884543, 2022). "High DDR2 expression predicts poor prognosis in ovarian cancer." (PMID 35884543, 2022). "ELMO1 and DDR2 have been demonstrated to mediate ovarian cancer progression." (PMID 36059959, 2022). "Interestingly, TWIST1 has been reported to regulate DDR2 expression in ovarian cancer and was found to be a shared effector of FOXQ1 and SNAI1 in this study." (PMID 36713812, 2022). "We had previously identified that tumor DDR2 regulates metastasis in ovarian cancer." (PMID 35884543, 2022).
ovarian carcinoma (continued). "Stromal DDR2 is highly correlated with stromal POSTN expression in ovarian cancer patient tumors." (PMID 35884543, 2022). "DDR2 has been reported to be induced by TWIST1 in ovarian cancer." (PMID 36713812, 2022). "Second, the expression of ATX is closely correlated with that of DDR2 in ovarian cancer patients." (PMID 34065317, 2021). "Importantly, the DDR2 siRNA significantly attenuated LPA-induced ovarian cancer cell 2D invasion, as well as migration." (PMID 34065317, 2021). "Given that more than 40 times more LPA is observed in both the plasma and the ascites of ovarian cancer patients, and that DDR2 is associated with poor clinical outcomes in ovarian cancer patients, we explore the role of DDR2 in LPA-induced ovarian cancer cell invasion." (PMID 34065317, 2021). "In addition, pretreatment of the cells with a selective pharmacological inhibitor of ATX ablated ATX-induced DDR2 expression and ovarian cancer invasion." (PMID 34065317, 2021). "DDR2 increases metastasis in a peritoneal xenograft model of ovarian cancer." (PMID 33917302, 2021). "Deciphering the important roles of another type of RTK, DDR2, in ovarian cancer progression, we hypothesize the implication of DDR2 in LPA-induced ovarian cancer progression." (PMID 34065317, 2021). "Moreover, the ovarian cancer patient profiles of the GEPIA dataset showed a significant positive correlation of ATX (ENPP2) expression with DDR2 (DDR2) expression (r = 0.49, p = 3.1 × 10−32)." (PMID 34065317, 2021). "Moreover, DDR2 regulates tumor metastasis in ovarian cancer by modulating POSTN expression in CAFs." (PMID 40563472, 2025). "Given that DDR2-regulated arginase activity in CAFs affected ovarian cancer tumor collagen production, we asked whether stromal arginase-1 expression correlated with ovarian cancer patient survival." (PMID 37996700, 2024). "Thus, DDR2 expression in CAFs regulates the steps of ovarian cancer metastasis through periostin." (PMID 35884543, 2022). "Therefore, PI3K, Akt, HIF-1α, Twist1, and DDR2 may serve as effective targets to attenuate the invasion and metastasis of ovarian cancer cells." (PMID 34065317, 2021). "In addition, the silencing of DDR2 expression abolished ATX-induced ovarian cancer cell invasion." (PMID 34065317, 2021). "In addition, Twist1 was shown to induce DDR2 expression in ovarian cancer." (PMID 34065317, 2021). "In ovarian cancer cells, DDR2, activated by COL11A1, upregulates fatty acid metabolism via the DDR2-Src-Akt-AMPK signaling axis, contributing to cisplatin resistance." (PMID 40563472, 2025). "DDR2 activates the AKT/SNAI1 pathway to enhance hexokinase activity, thereby modulating glycolysis in ovarian cancer cells." (PMID 40563472, 2025). "To determine which cell(s) in the host tumor stromal compartment expressed DDR2, we first interrogated published human and BPPNM mouse ovarian cancer single-cell RNA sequencing datasets." (PMID 37996700, 2024). "We identify that the interaction between DDR2 and POSTN is important in CAFs and promotes tumor metastasis in ovarian cancer." (PMID 35884543, 2022). "DDR2 and POSTN signal through the PI3K/AKT and Src pathway and represent therapeutic targets in ovarian cancer." (PMID 35884543, 2022). "We and others have shown that ovarian cancer cells bind to COL11A1 through the integrin heterodimer α1β1 and DDR2." (PMID 33668097, 2021). "Collectively, the present study demonstrates that ATX, and thereby LPA, induces DDR2 expression through the activation of the PI3K/Akt/mTOR/HIF-1α/Twist1 signaling axes, aggravating ovarian cancer cell invasion." (PMID 34065317, 2021). "Investigating DDR2 signaling, collagen XIα1 is an ECM small fibrillar collagen regularly overexpressed in ovarian cancer (including cisplatin resistance or recurrent ovarian cancer)." (PMID 34805157, 2021).
ovarian carcinoma (continued). "We determined that DDR2/integrin α1β1 and Src/Akt signaling mediate COL11A1 induction of total and phosphorylated HSP27, and that HSP27 mediates COL11A1-induced ovarian cancer cisplatin resistance." (PMID 34638339, 2021). "In the following sections we summarize some of the key breast and ovarian cancer focused research characterizing DDR1 and DDR2 dysregulation." (PMID 34805157, 2021). "The schematic signaling pathway of LPA-induced DDR2 expression depicts the upregulation of DDR2 by LPA through coordinate activation of the PI3K/Akt/mTOR/HIF-1α signaling pathways and Twist1 expression to augment ovarian cancer cell invasion." (PMID 34065317, 2021). "In addition, DDR2 stabilizes SNAIL and upregulates activity of matrix metalloproteinases (MMP) in ovarian cancer." (PMID 35884543, 2022). "As such, pathways modulated by DDR2 and POSTN can represent therapeutic targets in ovarian cancer." (PMID 35884543, 2022). "Interestingly, DDR2 is a key transcriptional target of TWIST1 during cranial mesoderm development and in ovarian cancer cells, where TWIST1-dependent DDR2 expression was critical for EMT, migration, invasion, and in vivo metastasis." (PMID 34716856, 2022). "Meanwhile, another EMT-TF, Twist1, was recently identified as inducing DDR2 expression and ovarian cancer metastasis, suggesting that morphological changes by EMT-TFs might be a driving force for DDR2 expression and ovarian cancer progression." (PMID 34065317, 2021). "However, the silencing of DDR2 expression significantly inhibited ATX- and LPA-induced ovarian cancer cell invasion." (PMID 34065317, 2021). "Interestingly, Ddr2, Ereg, Glipr1, Calcr, and Ankrd1, all up-regulated in STOSE cells, have been shown to be up-regulated in primary tumors and ovarian cancer cells." (PMID 24672774, 2014). "Furthermore, discoidin domain receptor tyrosine kinase 2 (DDR2) is upregulated in recurrent breast tumor cells, with sensitivity to ferroptosis enhanced by YAP/TAZ activation, which is unknown in ovarian cancer." (PMID 36090052, 2022). "Collectively, our results show for the first time that LPA induces DDR2 expression and consequent ovarian cancer cell invasion through the HIF-1α and Twist1 signaling axes, reinforcing the significance of LPA and the transactivation between GPCR and RTK in ovarian cancer progression." (PMID 34065317, 2021). "Interestingly, DDR2 knockdown significantly abrogated COL11A1-induced FASN overexpression while ITGA1 knockdown only slightly reduced FASN expression (data not shown), suggesting that DDR2 might be the predominant receptor that mediates COL11A1-induced FASN expression in ovarian cancer cells." (PMID 32312965, 2020).
breast tumor (19 papers, 2019 to 2026). "For example, DDR2 in cancer-associated fibroblasts (CAFs) increases tumor stiffness by reorganizing type I collagen fibrils at the tumor-stromal boundary, thereby promoting lung metastasis of breast tumors." (PMID 36656123, 2023). "In murine models of breast tumor, Longmore’s group demonstrated that DDR2, primarily expressed in CAFs, reorganizes collagen fibers at the tumor-stromal boundary, increasing stiffness and promoting metastasis, by generating a physically permissive TME." (PMID 41492134, 2026). "DDR2 is highly expressed in recurrent breast tumor cells displaying EMT features and promotes ferroptosis by activating YAP/TAZ." (PMID 41492134, 2026). "WRG-28, a small molecule targeting the extracellular domain of DDR2, induces a conformational change that disrupts DDR2′s interaction with collagen, thereby preventing breast tumor metastasis." (PMID 40563472, 2025). "For example, in cancer-associated fibroblasts, DDR2 activates β1 integrin activity via RAP1 stimulation of Talin1 and Kindlin2 to promote breast tumor metastasis." (PMID 39746922, 2025). "In breast tumor CAFs, the action of DDR2 has been shown to contribute to the production of collagens, by affecting mRNA synthesis." (PMID 37996700, 2024). "In depth, 75% of the low DDR2 expressing tumors exhibited low α-SMA staining, while CAFs infiltration was high in only 25% of the low DDR2 levels breast tumors." (PMID 35711892, 2022). "Here, we demonstrate that the action of DDR2 in both breast tumor cells and breast tumor stromal CAFs also affects their paracrine regulation of tumor cell invasion and migration." (PMID 34477203, 2021). "In a mouse model of spontaneous breast tumor development, inhibition of DDR2 expression by gene ablation largely reduces metastasis without affecting lung tumor growth." (PMID 33917302, 2021). "In lung metastases of breast tumor cells, DDR2 expression by tumor cells is important for metastasis development, but its expression in the metastatic niche is dispensable." (PMID 33917302, 2021). "The action of DDR2 in breast tumor cells is critical for their capacity to invade through the basement membrane and migrate through collagen-rich ECM so as to metastasize." (PMID 34477203, 2021). "The action of DDR2 in breast tumor cells is critical for in vivo lung metastasis in syngeneic orthotopic transplant and spontaneous genetically engineered mouse cancer models." (PMID 34477203, 2021). "DDR2 is also involved in breast tumor invasion by inducing mesenchymal phenotype, invasion, and metastasis." (PMID 35004699, 2021). "The action of the RTK DDR2 in breast tumor stromal CAFs has been shown to contribute to the development of breast tumor stiffness by influencing ECM production and mechanical remodeling through control of full activation of collagen binding integrins." (PMID 34477203, 2021). "We have found that in both human and mouse breast tumor cell lines and breast tumor CAFs, DDR2 does indeed exhibit tyrosine kinase-independent actions that can support tumor cell invasion and metastatic progression in vivo." (PMID 34477203, 2021). "Herein, we show that DDR2, in breast tumor CAFs, controls collagen binding Integrin activation by activating RAP1 to regulate Talin1 and Kindlin2 activity and, or recruitment to cell surface integrin." (PMID 31144616, 2019). "We can exclude the action of DDR2 in tumor cells as contributing to breast tumor stiffness since deletion of Ddr2 in breast epithelial cells only, with either MMTV-Cre or K14-Cre, did not affect primary tumor matrix production or organization." (PMID 31144616, 2019). "Collagen fiber organization in breast tumors from ubiquitous Ddr2-/- mice are more benign or less supportive of tumor invasion and spread and these mice develop significantly reduced lung metastases." (PMID 31144616, 2019).